CRP (C-reactive protein)
Diseases named in the same sentence as CRP in open-access papers (continued):
Sharing a sentence is not in itself a finding about the gene and the disease.
Stroke (continued). "Although our subgroup analysis suggests there is not a significant correlation between Hs-CRP and cognitive decline after stroke, there are studies indicating a relationship between Hs-CRP and non-vascular cognitive functions." (PMID 37509012, 2023). "C-reactive protein (CRP) is a sensitive, but not specific, marker of systemic inflammation that has been related to stroke risk in the community-dwelling population and risk of ischemic recurrence in patients who had a lacunar stroke." (PMID 35163423, 2022). "Inflammatory marker CRP was highly increased in both stroke patients with and without OD vs. HR subjects." (PMID 36703642, 2022). "In this large cohort study using a prospectively maintained stroke register, co-elevation of WCC and CRP at admission predicted poor outcomes in ICH: patients were more likely to have a poor functional outcome, die during admission, be dead at 90 days, and be dead at 1 year." (PMID 35869372, 2022). "The C-reactive protein-to-albumin ratio (CAR) is a new index that reflects the overall inflammatory status of patients with major diseases; however, no studies have reported the relationship between CAR and young stroke." (PMID 36457873, 2022). "In the present study, in patients with periodontal disease, as in patients without periodontal disease, a significant decrease in CRP and the number of leukocytes in the blood were observed on the seventh day of stroke when compared to the first one." (PMID 35893412, 2022). "In a recent meta-analysis of 13 cohort studies, 3536 participants demonstrated an obvious difference between higher CRP levels and PSD over 1 month post-stroke, but not between higher CRP levels and PSD within 1-month post-stroke." (PMID 36009095, 2022). "CRP levels showed a not significant tendency to be higher in female stroke patients compared to male stroke patients (14.8 ± 30.1 mg/L versus 8.2 ± 19.1 mg/L; T = 1.857, p = 0.065)." (PMID 36233669, 2022). "CRP retained its statistical significance after full adjustment for all comorbidities and demographics, irrespective of stroke at baseline (HR 1.47 (1.15–1.87))." (PMID 35042473, 2022). "CRP is elevated in persons with chronic SCI, is an important predictor of cardiovascular health, and can predict myocardial infarction and stroke." (PMID 35222077, 2022). "Baseline CRP measurements have been found to be higher in men who went on to have an AMI (1.51 vs. 1.13 mg/L) or stroke (1.38 vs. 1.13 mg/L) compared with men who did not, and the risk of AMI increased with each quartile increase of CRP levels." (PMID 35159397, 2022). "Residual blood was obtained from all the patients on the first, third and seventh days after their ischemic stroke and the concentrations of suPAR and C-reactive protein (CRP), as well as the number of leukocytes and National Institute of Health’s Stroke Scale (NIHSS) scores, were evaluated." (PMID 35330458, 2022). "Recent evidence focuses on the relationship between elevated-CRP levels and ischemic stroke, fatal stroke, non-fatal stroke, and transient ischemic attack." (PMID 36262245, 2022). "In the Circulatory Risk in Communities Study (CIRCS), there was a positive association between high serum CRP levels and risk of PSD, but not between high CRP levels and risk of dementia development without a history of stroke." (PMID 34884906, 2021). "Using the univariate analysis, the variables showing with a high stroke risk positive or negative correlation were determined as white blood cell (r = −256, p = 0.002), LDL-C (r = 346, p < 0.001), CRP (r = 382, p < 0.001), and endocan (r = 301, p < 0.001)." (PMID 33443627, 2021). "Numerous inflammatory mediators in the peripheral circulation, such as C-reactive protein (CRP) and interleukin-6 (IL-6), are altered in the acute phase of stroke and could have a role as biomarkers of prognosis or impending complications." (PMID 34753981, 2021).
Stroke (continued). "The proportion of males was also presented and was not significantly different between the non-stroke and stroke groups of patients with a CRP level >0.10 mg/dL (P = 0.396)." (PMID 34135849, 2021). "The frequencies of myocardial infarction among cardiovascular diseases were higher in the H-WBC regardless of serum CRP concentrations among all groups, whereas stroke was highest in the H-WBC+H-CRP." (PMID 34371818, 2021). "In addition to the major reduction in stroke occurrence, a statistically significant decrease in inflammatory burden (ESR, CRP) followed anti-TNF treatment initiation." (PMID 35095905, 2021). "Nevertheless, calprotectin prognostic role and its association with other inflammatory biomarkers, such as CRP and NLR, have not yet been studied in stroke patients." (PMID 33402185, 2021). "The second aim was to investigate the correlation with monitoring markers used in stroke management such as the Glasgow Coma Scale (GCS), C-reactive protein (CRP), complete blood count (CBC), and kidney battery, and to explore the usefulness of FC in stroke monitoring." (PMID 35011900, 2021). "Finally, impaired individuals were found to have higher baseline and discharge national institutes of health stroke scale (NIHSS) scores, with higher C-reactive protein levels (CRP) and white blood cell counts (WBC)." (PMID 34512528, 2021). "Similarly, subgroups of stroke patients were assembled for SNP frequency comparisons based on WBC, CRP levels, TOAST classification and short term disease outcome (NIHSS score change)." (PMID 34680558, 2021). "In the second study, atorvastatin prescription for 3 and 30 days did not reduce CRP in stroke patients and did not appear to modify infarct growth substantially." (PMID 34489618, 2021). "CRP and NLR have been shown as potential biomarkers or therapeutic targets for stroke management." (PMID 33402185, 2021). "Despite the published clinical trials reporting the effects of statins on the CRP level in stroke patients, the findings of these studies have not been systematically reviewed." (PMID 34489618, 2021). "We found that there were significant differences among the three groups in terms of age, BMI, history of hyperlipemia, history of stroke, smoking history, type of CAD, percentage of diffuse and CTO disease, HbA1c, FBG, TC, TG, LDL-C, HDL-C, hs-CRP, and creatinine." (PMID 34489866, 2021). "Here, we report a platform for biosensing based on chelated Eu3+ against a range of proteins including biomarkers of cardiac injury (human myoglobin), stroke (glial fibrillary acidic protein (GFAP)), inflammation (C-reactive protein (CRP)) and colorectal cancer (carcinoembryonic antigen (CEA))." (PMID 33513673, 2021). "Although the CRP level did not significantly predict stroke, these findings will be helpful for future research." (PMID 34135849, 2021). "A meta‐analysis showed that IPOC may provide brain protection after stroke that can significantly reduce the recurrence of stroke and transient ischemic attacks (TIA), while also reducing the NIHSS score, modified Rankin Scale, and highly sensitive CRP." (PMID 34559467, 2021). "LPS levels correlated with CRP and LBP levels in stroke and TIA." (PMID 33753837, 2021). "When analyzed per one unit increase in log(hs-CRP), again no relation was found for myocardial infarction (HR 1.14, 95%CI 0.94–1.38), stroke (HR 0.83, 95% CI 0.64–1.08) or cardiovascular events (HR 1.08, 95% CI 0.94–1.25)." (PMID 34753497, 2021). "Thus, we explored whether LPS (Lipopolysaccharide) or LTA (Lipoteichoic acid) levels are elevated in different causes of stroke and correlated with CRP levels since TLR4 is the receptor for Gram-negative bacterial LPS and TLR2 is the receptor for Gram-positive bacterial LTA, respectively." (PMID 33753837, 2021).
Stroke (continued). "In the multivariate analysis, higher CRP level was related to depressive symptoms at day 8 (OR: 2.23, 95%CI: 1.28–3.90, P < 0.01), but not depressive symptoms 3 months after stroke (OR: 1.13, 95%CI: 0.59–2.17, P = 0.71)." (PMID 31996746, 2020). "More severe strokes in the AIS + D group compared to the AIS group have greater potential to contribute to the observed elevations of serum IL-6 and CRP in the former group, as both IL-6 and CRP in blood are elevated by ischemic stroke." (PMID 32758167, 2020). "Among Chinese adults, who have low mean LDL-C, CRP, but not fibrinogen, was independently associated with increased risks of MCE and stroke." (PMID 32221345, 2020). "Our findings also show an important role of innate immunity in first-ever stroke and CHD risk in the general population, independent of hs-CRP level or lipid-lowering medication use." (PMID 32379748, 2020). "The present study showed that HBOT for acute non-cardioembolic stroke can statistically decrease hs-CRP levels following HBOT (1 month after stroke)." (PMID 30208940, 2018). "The association between increased baseline hs-CRP and subsequent PVC events remained sigfnicaint in men and in those without history of myocardial infarction or stroke." (PMID 29581482, 2018). "Although none of the patients with elevated Hcy or CRP that returned to the hospital had a recurrent stroke, the number of patients was too small to draw a conclusion and should not negate the potential benefits of lowering these levels in patients." (PMID 30613458, 2018). "The serum levels of TNF-α, CRP, TGF-β, IL-4, IL-6, IL-10, IL-17, and IL-23 were all increased on days 1, 3, and 7 after stroke when compared with levels in the control group (all p < 0.05); however, the content of IFN-γ was lower in stroke patients than in controls at each time point (p < 0.01)." (PMID 27682880, 2017). "Total cholesterol (β = -0.008, P = 0.001) and high sensitivity C-reactive protein (β = -0.474, P = 0.012) were inversely correlated with the △LF/HF ratio in patients without stroke." (PMID 28302058, 2017). "Raised CRP levels are also seen with non-infective pathologies such as pulmonary embolism, malignancies, trauma, and stroke." (PMID 26937636, 2016). "Furthermore, score of National Institutes of Health Stroke Scale (NIHSS), total T4, free T4, and C-reactive protein at admission were significantly higher in patients with poor functional outcome, whereas free T3 and total T3 were significantly lower." (PMID 27375741, 2016). "Plasma LCN2 levels did not correlate with maximum CRP levels measured one week after stroke (rS = 0.23; p = 0.12)." (PMID 27152948, 2016). "In AD patients, we showed that expression of mCRP, but not native CRP was expressed strongly in microvessels but only following ischaemic stroke and in stroke-affected regions." (PMID 26335098, 2015). "Single-biomarker models of CRP, triglycerides, and glycohemoglobin were strongly associated with each CVD, though the associations between triglycerides and stroke or MI were not significant." (PMID 25788869, 2015). "Our data show that levels of the pro- and anti-inflammatory markers IL-6, CRP and IL-10 differ as early as at 6 h after stroke onset between patients with and without post-stroke infection." (PMID 25613713, 2015). "Importantly, stroke severity (NIHSS>15 points), CRP levels at admission, and the intake of platelet inhibitors in the days before blood withdrawal each independently predicted VWF levels." (PMID 24937073, 2014). "Adjusting for age and sex did not attenuate the trend in all stroke and IS in both groups of elevated hs-CRP groups (≥1 mg/L)." (PMID 25191699, 2014). "The aim of the present study was to clarify the contribution of inflammatory mediator level, including WBC, HCY, and high sensitivity C-reactive protein (hs-CRP), to categorized middle cerebral artery (MCA) stenosis as well as stroke severity by means of 1-year modified Rankin Scale (mRS)." (PMID 24023414, 2013).
Stroke (continued). "IL-6, CRP, age, NIHSS score and dysphagia may be predictive factors for the occurrence of pneumonia on the day of stroke symptom onset." (PMID 23935729, 2013). "In healthy persons without hyperlipidemia but with elevated high-sensitivity CRP levels, rosuvastatin, which lowered high-sensitivity CRP as well as cholesterol levels, reduced the incidence of stroke and myocardial infarction by 50% relative to placebo." (PMID 23431245, 2013). "Components of the early phase reaction such as CRP, cytokines, and fever are frequently increased after stroke without other evidence of infection." (PMID 24069356, 2013). "IL-6, CRP, age, NIHSS score and dysphagia may predict the occurrence of pneumonia on the day of stroke symptom onset." (PMID 23935729, 2013). "In healthy persons without hyperlipidemia but with elevated high-sensitivity CRP level, rosuvastatin, which lowers high-sensitivity CRP as well as cholesterol level, reduced the incidence of stroke and myocardial infarction by 50% relative to placebo." (PMID 23326018, 2012). "CRP has been shown to predict an increased risk for CVD, as well as stroke and noninsulin-dependent diabetes." (PMID 22110481, 2012). "The rates for the combined endpoint of stroke, AMI and death in the different quartiles of peak CRP were twenty-four (28.2%), thirty-one (37.8%), thirty-four (40.5%) and fifty-two (62.7%) in the first, second, third and fourth quartile, respectively (p < 0.0005)." (PMID 19583836, 2009). "IL-6 is induced by tumour necrosis factor α and IL-1β, and then leads to the releases of CRP, fibrinogen, and cell adhesion molecules, though the cellular origin of IL-6 after stroke is not clear." (PMID 19901973, 2009). "CRP and NIH stroke scale (NIHSS) were measured at the time of admission." (PMID 19400931, 2009). "On these days, the upper limits of a computed reference interval (mean + 1.96SD on the log transformed values) were 47.8 mg/L and 42.7 mg/L respectively, meaning that no more than 2.5% of stroke patients without an overt complication can be expected to have a higher CRP value." (PMID 40447994, 2025). "ICI’s composite nature (CRP + D-dimer/WBC) captures this synergy, where a high ratio may signal excessive inflammatory–thrombotic drive with limited immune reserve, common in severe strokes." (PMID 41002924, 2025). "Second, we were able to investigate a range of systemic inflammation biomarkers, including CRP and differential leukocyte count, and composite measures such as LMR, NLR, PLR, and SII, as well as a range of outcomes: incident CVD and its main subtypes, including IHD, stroke and heart failure." (PMID 40234895, 2025). "However, CRP did not significantly mediate the stroke–sarcopenia relationship due to a low indirect effect." (PMID 40791098, 2025). "While not yet tested in ICH, this method could be applied to stroke patients: lowering systemic CRP might prevent its conversion to mCRP at the injury site, blunting systemic and neuroinflammation." (PMID 40649973, 2025). "Among patients with AF-related stroke, the predictors of severe stroke (NIHSS ≥ 15) included high ATRIA score (OR = 1.712, 95% CI: 1.348–2.173, p < 0.001), reduced EF (OR = 0.957, 95% CI: 0.918–0.999, p = 0.044), and elevated CRP levels (OR = 1.022, 95% CI: 1.007–1.037, p = 0.004)." (PMID 40649038, 2025). "The Justification for the Use of Statins in Prevention: An Intervention Trial Evaluating Rosuvastatin (JUPITER) trial aimed to assess potential benefits with respect to stroke occurrence in patients exhibiting a C-reactive protein (CRP) increase (>2 mg/L) and no hypercholesterolemia." (PMID 40149635, 2025). "Since there was no medical diagnosis to justify the elevated CRP values, besides vascular epilepsy, and the patients’ blood tests were conducted less than a year after the stroke, this timing might also explain why the CRP levels remained elevated for so long." (PMID 39634547, 2024).
Stroke (continued). "Although high CRP values may be due to the medical diagnosis of vascular epilepsy or peripheral inflammatory response after stroke, we have no clinical reason to prove this." (PMID 39634547, 2024). "Furthermore, a comprehensive evaluation of clinical trials revealed significant improvements in cardiovascular events, including reductions in both fatal and non-fatal myocardial infarctions and strokes, alongside decreased CRP levels." (PMID 39149678, 2024). "In other words, through serum protein profiling in patients with stroke and AF and patients with stroke but without AF, traces of inflammatory activity such as CRP, LBP, and A1AG1 were confirmed in patients with stroke and AF, and changes in thyroid hormone transport protein." (PMID 38886511, 2024). "Therefore, it is crucial to include objective and readily available predictors for better predictive model performance, such as inflammatory biomarkers interleukin-6 (IL-6) or C-reactive protein (CRP), which have been shown to be related to an increase in OSA in stroke patients in previous studies." (PMID 38268059, 2024). "Additionally, previous studies have indicated that inflammatory mediators such as C-reactive protein (CRP) and interleukin-6 (IL-6) undergo changes during the acute phase of stroke, serving as potential biomarkers for stroke prognosis or imminent complications." (PMID 38509177, 2024). "However, some studies suggest that elevated hs-CRP levels do not seem to independently affect the outcome in patients with stroke." (PMID 37342777, 2023). "Our statistical results suggested that the concentrations of peripheral CRP may be significantly increased for CD patients after stroke, compared to those of non-CD patients." (PMID 37509012, 2023). "The present findings showed that CRP has a negative effect on the prognosis in stroke patients." (PMID 37612344, 2023). "Indeed, our findings for models predicting incident stroke revealed that elevated CRP, as opposed to low wealth, were key." (PMID 37808231, 2023). "A case-control study of 680 patients with minor stroke or TIA, with systematic exclusion of patients with confounding infection or pro-inflammatory diseases, found that higher baseline levels of IL-6, IL-8 and high sensitivity (hs) CRP independently predicted one-year recurrent vascular events." (PMID 41541100, 2023). "By contrast, the Northern Manhattan Study (NOMAS) of 2,240 stroke-free community participants suggested that hs-CRP could predict mortality but not ischemic stroke." (PMID 35399841, 2022). "The Cardiovascular Health Study of 5417 individuals aged 65 years or older without previous stroke, after 10.2 years of follow-up, found that the adjusted HR in the 4th quartile of CRP level was 1.60 (95% CI: 1.23–2.08) for ischemic stroke relative to the 1st quartile." (PMID 35399841, 2022). "However, previous studies were limited to using elevated-CRP levels as a predictor of IS, not overall stroke." (PMID 36262245, 2022). "Therefore, CRP and CAR may be equally helpful in predicting the prognosis of neurocritically ill patients with stroke and in making early decisions for their treatment." (PMID 36079002, 2022). "Therefore, CRP and CAR may be equally helpful to predict the prognosis of neurocritically ill patients with stroke and to make early decisions for their treatment." (PMID 36079002, 2022). "The panel of biochemical tests should be expanded to include CRP in saliva, and the concentration of IL-1β, OPG, RANKL and MMP-8 in the blood, which would allow for a discussion of the results in saliva in the context of the analyzed role of periodontal disease in the course of stroke." (PMID 35893412, 2022). "With the additional adjustment for C-reactive protein, the same results as those for all stroke and ischaemic stroke, but not haemorrhagic stroke, were obtained for the WBC count (4 ~ 10*10^9/L) and the NEUT count (the NEUT counts in the top 1% and bottom 1% at baseline were excluded)." (PMID 34856939, 2021).